CTTN (cortactin)
Diseases named in the same sentence as CTTN in open-access papers (continued):
Sharing a sentence is not in itself a finding about the gene and the disease.
squamous cell carcinoma (5 papers, 2011 to 2025). A carcinoma arising from squamous epithelial cells. "Cortactin interacts with the Arp2/3 complex that there is a study showing that overexpression of cortactin in patients is related to high grade tumors, metastasis and poor survival in squamous cell carcinomas." (PMID 32597160, 2020). "We showed that laminin-111 peptide C16 increased invadopodia activity over time and stimulated cortactin phosphorylation in cell lines derived from squamous cell carcinoma (CAL27) and fibrosarcoma (HT1080), two invasive tumors with poor prognosis." (PMID 27323814, 2016). "Immunostaining revealed a progressive increase in cortactin expression from normal tissue to LSIL, HSIL, and squamous cell carcinoma (SCC), with the strongest cytoplasmic staining observed in SCC cases." (PMID 41148856, 2025). "Other markers such as cortactin, NANOG, and SOX2 protein expression are frequent in squamous cell carcinoma." (PMID 36980171, 2023).
gastric adenocarcinoma (4 papers, 2021 to 2026). "To investigate the role of cortactin in these phenotypes in more detail, we produced a complete knockout mutant of cortactin in the gastric adenocarcinoma cell line AGS by CRISPR-Cas9." (PMID 35055951, 2021).
leukemia (4 papers, 2018 to 2022). A malignant (clonal) hematologic disorder, involving hematopoietic stem cells and characterized by the presence of primitive or atypical myeloid or lymphoid cells in the bone marrow and the blood. "This indicates that both cortactin and HS1 are involved in the capacity of Wnt5a to enhance leukemia-cell motility and that the deficiency of one cannot be fully compensated by the other." (PMID 30568170, 2019). "For instance, Calcineurin, a serine‐threonine protein phosphatase and a biomarker of T‐ALL leukemia‐initiating cells, regulates the cell surface expression of CXCR4 in a cortactin‐dependent manner." (PMID 36054080, 2022). "Collectively, these studies reveal that Wnt5a induces ROR1 to complex with cortactin/HS1/ARHGEF1 at P841, which induces phosphorylation of cortactin and HS1, activation of ARHGEF1 and RhoA, thereby enhancing leukemia-cell migration." (PMID 30568170, 2019). "The role of cortactin in in vivo migration and extramedullary infiltration was explored in REH- and patient-derived leukemia xenografts (REH-DX and PDX, respectively)." (PMID 30573781, 2019). "Here we report our studies evaluating whether cortactin is recruited to ROR1 upon stimulation with Wnt5a, undergoes tyrosine phosphorylation, and recruits/activates ARHGEF1 to promote F-actin polymerization and leukemia-cell migration." (PMID 30568170, 2019).
lung disorder (4 papers, 2021 to 2024). A disease involving the lung. "CTTN (OMIM 164765) is implicated in lung disease among patients of African descent,63RSBN1L (HGNC 24765) is upregulated in COVID-19,64 and RASGRP4 (OMIM 607320) regulates dendritic and mast cell function." (PMID 36306130, 2022). "This figure illustrates some functional changes that have been reported to involve CTTN and can be associated with important pulmonary disease processes." (PMID 35562995, 2022). "We then provide insights into how CTTN function affects the pathophysiology of multiple lung disorders, including acute lung injury syndromes, COPD, and asthma." (PMID 35562995, 2022). "In summary, further study of the many pathophysiologic mechanisms involving CTTN holds promise for advancing our understanding of multiple problematic lung diseases." (PMID 35562995, 2022). "A recent report identified the CTTN gene as one of the most highly altered in terms of methylation status in smokers, suggesting a potential role for CTTN in CS-induced pulmonary diseases." (PMID 34831092, 2021).
metastatic disease (4 papers, 2011 to 2020). "Expression of cortactin, CD44, NBS1, CXCR4, Snail and VEGF in patients with metastatic disease has been correlated to the development of distant metastases." (PMID 24212639, 2011). "Phospho-cortactin staining intensity was absent/negative in 5 (17.2%), low in 9 (31.0%) and high in 15 (51.8%) of primary tumors, while staining was negative in 0, low in 8 (22.9%) and high in 27 (77.1%) metastatic tumors." (PMID 30976201, 2019). "In agreement with our above data, the mRNA levels of ABL2 and CTTN, but not of ABL1, were significantly higher in metastatic tumors compared with tumors that did not metastasize." (PMID 29774130, 2018).
non-small cell lung carcinoma (4 papers, 2018 to 2022). A group of at least three distinct histological types of lung cancer, including non-small cell squamous cell carcinoma, adenocarcinoma, and large cell carcinoma. "Hepatocyte growth factor (HGF) and phorbol 12,13-dibutyrate (PDBu) can induce CTTN expression, motility, and invasion ability, as well as invadopodia formation in non-small cell lung cancer (NSCLC)." (PMID 29986736, 2018).
osteosarcoma (4 papers, 2014 to 2017). A usually aggressive malignant bone-forming mesenchymal neoplasm, predominantly affecting adolescents and young adults. "The potential of cortactin overexpression as a biomarker for osteosarcoma is, in fact, consolidated and transcriptomic profiling has shown cortactin to be overexpressed in pediatric osteosarcoma." (PMID 28439237, 2017). "Previous reports showed that a significant correlation between CTTN overexpression and poor prognosis in osteosarcoma." (PMID 24551190, 2014). "Interestingly, endogenous phospho-STIM1 has a high level of co-localization with endogenous cortactin, as we observed not just in C2C12 myoblasts, but also in the osteosarcoma cell line U2OS and in HeLa cells." (PMID 28341841, 2017).
prostate carcinoma (4 papers, 2017 to 2025). A carcinoma that arises from epithelial cells of the prostate gland. "Cortactin plays a crucial role in the migration, invasion, and metastasis of prostate cancer cells, and its overexpression is closely related to the malignant progression of cancer." (PMID 40507156, 2025). "piR-19166, downregulated in prostate carcinoma cells, inhibited cell migration by up to 40% in vitro and reduced metastasis by 75% in a mouse model through suppression of CTTN mRNA, a key component of CTTN/MMPs signaling pathway responsible for metastasis." (PMID 40723836, 2025).
asthma (3 papers, 2017 to 2024). "In two independent case-control samples of AA and EA severe asthma cohorts, CTTN variant rs3802780 were identified as consistently associated with susceptibility to severe asthma." (PMID 39162263, 2024). "A total of 9 CTTN gene polymorphisms (SNPs) associated with asthma were identified, and a specific intronic SNP, rs3802780, showed a significant association with severe asthma, suggesting the importance of CTTN in altering the clinical phenotype." (PMID 35562995, 2022). "The genetic and epigenetic factors that influence the regulation of the CTTN promoter encoding cortactin, an important cytoskeletal protein and contributor to the severity of asthma and the ARDS, are unknown." (PMID 39162263, 2024). "Since cortactin regulates smooth muscle cell protrusion formation, it is likely that cortactin-associated migration may contribute to asthma pathogenesis." (PMID 28390425, 2017). "A common cortactin gene variation has been found to confer susceptibility of severe asthma." (PMID 28390425, 2017). "Further investigation will better define the role of CTTN in vascular barrier function, inflammation, and airway smooth muscle in the pathophysiology of asthma and COPD." (PMID 35562995, 2022). "CTTN is a cytoskeletal target gene whose coding variants (SNPs) also contribute to the genetic basis for observed ARDS health disparities in severe sepsis-induced ARDS and severe asthma in African Americans (AA) and/or European Americans (EA)." (PMID 39162263, 2024). "The CTTN gene was identified to be in proximity with asthma-related genes in the 11q13 chromosome." (PMID 35562995, 2022). "Thus, profilin plays a vital role in the regulation of airway hyperresponsiveness and smooth muscle contraction via processes involving CTTN and c-Abl, suggesting a potentially novel role of CTTN in asthma pathogenesis." (PMID 35562995, 2022).
autoimmune disease (3 papers, 2015 to 2023). A disorder resulting from loss of function or tissue destruction of an organ or multiple organs, arising from humoral or cellular immune responses of the individual to their own tissue constituents. "Together these findings reveal cortactin as a possible target for mitigation of T cell driven autoimmune diseases." (PMID 37485352, 2023). "Anti-cortactin abs were identified by Gallardo and coworkers as potential autoantibodies in seronegative MG but they were found in 12,5% of patients with other autoimmune disorders and also in 5,2% of healthy controls." (PMID 26284792, 2015).
endothelial dysfunction (3 papers, 2016 to 2022). In vascular diseases, endothelial dysfunction is a systemic pathological state of the endothelium (the inner lining of blood vessels) and can be broadly defined as an imbalance between vasodilating and vasoconstricting substances produced by (or acting on) the endothelium. "In this study, we provide evidence that the endothelial phenotype of cortactin-deficient mice is caused by increased actomyosin contractility as a consequence of decreased ADM secretion leading to endothelial dysfunction as manifested by increased permeability." (PMID 27357373, 2016).
esophageal squamous cell carcinoma (3 papers, 2020 to 2025). Esophageal squamous cell carcinoma (ESCC) is a type of esophageal carcinoma (EC) that can affect any part of the esophagus, but is usually located in the upper or middle third. "Previous studies have implicated CTTN in promoting esophageal squamous cell carcinoma via the PI3K/AKT pathway." (PMID 41214391, 2025). "Previous studies have shown that CTTN promotes esophageal squamous cell carcinoma by activating PI3K/AKT." (PMID 41214391, 2025). "CTTN can be a new molecular therapeutic target for esophageal squamous cell carcinoma, and it also promotes the proliferation of CRC cells." (PMID 34575665, 2021).
fibrosarcoma (3 papers, 2016 to 2020). A malignant mesenchymal fibroblastic neoplasm affecting the soft tissue and bone. "Similar to MDA-MB-231 cells, collagenolytic invadopodia enriched in cortactin, TKS5, and FGD1 were observed in association with the collagen fibers in HT-1080 fibrosarcoma cells." (PMID 32673397, 2020).
lung squamous cell carcinoma (3 papers, 2021 to 2024). "The current study demonstrates that CX3CL1 promotes the phosphorylation of cortactin via c‐Src and c‐Abl signalling pathways, and further promotes the migration and invasion of lung adenocarcinoma A549 cells and lung squamous cell carcinoma H520 cells." (PMID 33191645, 2021).
oral cancer (3 papers, 2019 to 2022). "Cortactin (CTTN) gene encodes a protein, cortacn, which plays an essential role in the migration of oral carcinoma cells by regulating filamentous actin and prominent structures on cell membranes." (PMID 35449571, 2022).
pancreatic ductal adenocarcinoma (3 papers, 2019 to 2021). An infiltrating adenocarcinoma that arises from the epithelial cells of the pancreas. "However, little is known about the biological role of cortactin in the progression of pancreatic ductal adenocarcinoma (PDAC)." (PMID 30976201, 2019). "In pancreatic ductal adenocarcinoma, the overexpression and phosphorylation of cortactin promotes the occurrence of the EMT, followed by the metastasis and migration of pancreatic ductal carcinoma." (PMID 33195233, 2020). "Interestingly, it was recently proven that GSN interacts with cortactin in human pancreatic ductal adenocarcinoma cells (PDAC), though the authors showed GSN co-localization with cortactin at the cell periphery and not in invadopodium." (PMID 34440617, 2021).
triple-negative breast carcinoma (3 papers, 2023 to 2026). An invasive breast carcinoma which is negative for expression of estrogen receptor (ER), progesterone receptor (PR), and human epidermal growth factor receptor 2 (HER2). "Of the 333 patients with high cortactin expression, 204, 58, and 71 had luminal, HER2, and triple-negative breast cancer (TNBC), respectively." (PMID 37761244, 2023).
viral infection (3 papers, 2020 to 2024). "Despite the growing body of knowledge on the function of cortactin, relatively little is known regarding the involvement of cortactin in barrier dysfunction caused by viral infection." (PMID 35848790, 2022). "CTTN has been shown to promote viral infection in several virology studies, including the Influenza virus, Hepatitis C Virus (HCV), and Rotavirus (RV)." (PMID 38612921, 2024). "In conclusion, further research is required on how CTTN interacts with NiV F and G proteins and how it is involved in viral infection." (PMID 38612921, 2024). "Although our study sheds light on the important role of actin-binding proteins in the epithelial response to viral infection, we acknowledge that the mechanistic link between RSV infection and cortactin decrease is still missing in the current study, and warrants further investigation." (PMID 35848790, 2022). "Although we recognize that dynamic phosphorylation could serve as a general mechanism among different viral infections, we have not investigated the changes in phosphorylation of the remaining cortactin after RSV infection, leaving it a potential subject for future studies." (PMID 35848790, 2022).
B-cell acute lymphoblastic leukemia (2 papers, 2019 to 2021). A neoplasm of lymphoblasts committed to the B-cell lineage, typically composed of small to medium-sized blast cells. "Therefore, the aim of the present work is to assess the clinical value of cortactin and HS1expression in B-cell acute lymphoblastic leukemia." (PMID 33773540, 2021). "This study aimed to assess the prognostic value of cortactin and HS1 genes expression in adult B-cell acute lymphoblastic leukemia." (PMID 33773540, 2021).
breast adenocarcinoma (2 papers, 2021 to 2023). "Cortactin might increase the risk of breast adenocarcinoma metastasis to bone marrow mediated by hyaluronan/cluster of differentiation-44 (CD44) signaling in MCF-7 cell lines indicating that the expression level of CTTN can be positively regulated by CD44." (PMID 33407452, 2021). "Accordingly, 60 min after plating MDA-MB-231 breast adenocarcinoma cells on the fibrillar network, invadosomes were detected as F-actin-, cortactin- and TKS5-enriched curvilinear structures that formed at contact sites between the PM and the underlying collagen fibrils." (PMID 37903910, 2023).
cervical cancer (2 papers, 2019 to 2023). A primary or metastatic malignant neoplasm involving the cervix. "We found that cortactin staining might be a useful molecular diagnostic aid for cervical cancer screening, based on its sensitivity and specificity." (PMID 36980391, 2023). "Cortactin may also be associated with E6/E7 RNA in HR-HPV-associated cervical cancer and is a potential diagnostic biomarker studied by our group." (PMID 36980391, 2023). "Meta-analyses have concluded that an overexpression of p16INK4A in cervical cancer relates to increased overall and disease-free survival rates, which differs from the function of cortactin." (PMID 36980391, 2023). "VEGF‐C can also reduce the expression of miR‐326 and increase the expression of cortactin through c‐Src signaling, leading to enhanced cervical cancer invasiveness." (PMID 31478352, 2019). "The expression of cortactin in cervical cancer, which is reported for the first time by our group, may act as a biomarker for cervical cancer progression." (PMID 36980391, 2023). "However, the cellular functions of cortactin in cervical cancer require further investigation." (PMID 36980391, 2023).
colon adenocarcinoma (2 papers, 2013 to 2024). "We demonstrate Simultaneous CLEM (SCLEM) analyzing cell-cell connections and membrane protrusions in whole uncoated colon adenocarcinoma cell line cells stained for actin and cortactin with AlexaFluor488." (PMID 23409024, 2013).
colorectal adenocarcinoma (2 papers, 2011 to 2016). The most common type of colorectal carcinoma. "Some of the identified proteins, e.g. IgGF-binding protein, Cytokeratin-18, Src substrate cortactin are typically overexpressed in colorectal adenocarcinoma cells." (PMID 21849038, 2011).
endometrial carcinoma (2 papers, 2021 to 2023). A malignant tumor arising from the epithelium that lines the cavity of the uterine body. "Quantitative PCR (qPCR) was used to determine the mRNA levels of CTTN in four endometrial cancer cell lines: Ishikawa, AN3CA, HEC-1-A, and HEC-1-B." (PMID 37970440, 2023). "However, the link between lncRNAs and cortactin in endometrial carcinoma remains unclear." (PMID 35178403, 2021).
gastric tumor (2 papers, 2021). "Taken together, we demonstrate here that the gastric carcinogen H. pylori profoundly induced cortactin phosphorylation at residue Y-470, which triggers cell scattering and elongation with a proposed, accompanying function in gastric tumor cell progression." (PMID 34439396, 2021).
glioma (2 papers, 2018 to 2020). A benign or malignant brain and spinal cord tumor that arises from glial cells (astrocytes, oligodendrocytes, ependymal cells). "CTTN was reported overexpressed in gliomas where its silencing significantly inhibit cell migration and invasion, as well as lamelipodia formation in tumor cells." (PMID 29872504, 2018).
histiocytic sarcoma (2 papers, 2016 to 2022). An aggressive malignant neoplasm with a poor response to therapy, usually presenting as stage III/IV disease. "Summarised, persistent CDV-Ond infection of canine histiocytic sarcoma cells reduced the cellular migration capacity in vitro, associated with a diminished cortactin accumulation at the cell periphery." (PMID 27911942, 2016). "The aim of the present study was to determine the impact of CDV infection on cell migration of canine histiocytic sarcoma cells (DH82 cells) with special emphasis on cortactin expression, gene regulation and possible functional implications." (PMID 27911942, 2016). "Similarly, a decrease in cortactin was observed during persistent morbillivirus infection in histiocytic sarcoma cells." (PMID 35848790, 2022). "Thus, the impact of persistent canine distemper virus infection on the cytoskeletal protein cortactin, which is frequently overexpressed in human cancers with poor prognosis, was investigated in vitro in a canine histiocytic sarcoma cell line (DH82)." (PMID 27911942, 2016). "However, the influence of modulating the cortactin expression in histiocytic sarcomas has not been investigated so far, despite the fact that histiocytic sarcoma cells link both, a cell type which typically is able to migrate and a malignant transformation of the cells." (PMID 27911942, 2016).
invasive breast carcinoma (2 papers, 2015 to 2023). A carcinoma that infiltrates the breast parenchyma. "In this study, we evaluated cortactin expression in 506 cases of invasive breast carcinoma and investigated the correlation between cortactin expression, clinicopathological characteristics, and patient survival." (PMID 37761244, 2023). "In conclusion, we investigated the clinicopathological significance of cortactin expression in 506 cases of invasive breast carcinoma." (PMID 37761244, 2023). "Of the 506 invasive breast carcinoma cases, 333 showed high cortactin expression, and 173 showed low cortactin expression following IHC staining." (PMID 37761244, 2023).
metastatic carcinoma (2 papers, 2014 to 2020). A carcinoma which has spread from the original site of growth to another anatomic site. "Cortactin overexpression could be associated with poor survival and aggressive behavior of metastatic cancers." (PMID 24465712, 2014).